KRT73 (keratin 73)
Description:
Has a role in hair formation. Specific component of keratin intermediate filaments in the inner root sheath (IRS) of the hair follicle (Probable).
Synonyms: CK-73; K73; K6IRS3; KRT6IRS3; IRT6IRS3
Tractability: PROTAC: ubiquitination databases record sites on it.
Gene: Protein-coding gene on chromosome 12 (52,607,570 to 52,618,559, reverse strand). Ensembl gene ENSG00000186049.
Pathways (Reactome):
Developmental Biology: Formation of the cornified envelope; Keratinization
Gene Ontology:
Molecular function: protein binding; structural constituent of skin epidermis
Biological process: intermediate filament organization; keratinization
Cellular component: extracellular exosome; nucleus; cytosol; keratin filament
Genetic constraint (gnomAD): Loss-of-function variants: 45 observed, 50.42 expected, observed/expected ratio (o/e) 0.89, 90% interval 0.7 to 1.14. The upper end of that interval is the gene's LOEUF score, 1.14, which puts it in group 5 of 6, group 1 being the genes least tolerant of losing a copy. Missense variants: 713 observed, 734.52 expected, observed/expected ratio (o/e) 0.97, 90% interval 0.91 to 1.03. Synonymous variants: 285 observed, 305.09 expected, observed/expected ratio (o/e) 0.93, 90% interval 0.85 to 1.03.
Homologues: Orthologues: chimpanzee KRT73 (99% identical), macaque KRT73 (98% identical), dog KRT73 (91% identical), pig KRT73 (87% identical), guinea pig KRT73 (86% identical), rabbit KRT73 (84% identical), rat Krt73 (84% identical), mouse Krt73 (84% identical). Paralogues in human: KRT71 (81% identical), KRT74 (73% identical), KRT72 (71% identical), KRT3 (60% identical), KRT76 (60% identical), KRT4 (59% identical), KRT5 (58% identical), KRT6A (58% identical), KRT6B (57% identical), KRT2 (57% identical), KRT6C (57% identical), KRT1 (57% identical), and 56 more.
Diseases named in the same sentence as KRT73 in open-access papers:
KRT73 is named in the same sentence as 11 diseases in open-access papers, as found by Europe PMC text mining. Sharing a sentence is not in itself a finding about the gene and the disease. The quoted sentences say what the papers report.
breast carcinoma (1 paper, 2021). "Another BRD4 inhibitor JQ1 along with MS417 were demonstrated to interfere with BRD4 binding to Keratin 73 (K73)/K76Ac2 on TWIST transcription factor and repress WNT5A expression, thus reversing EMT and metastasis of breast cancer in vitro and in vivo." (PMID 33803458, 2021).
colorectal cancer (1 paper, 2025). A primary or metastatic malignant neoplasm that affects the colon or rectum. "This study identified and validated a reproducible five-gene panel—DLG5, CD177, SH2D1B, NQO2, and KRT73—derived from whole-blood RNA, with strong diagnostic relevance for colorectal cancer (CRC)." (PMID 41373777, 2025).
diabetes (1 paper, 2025). "Through the analysis involving differential gene expression and machine learning-based feature selection, we identified a subset of key genes, including CNOT1, KRT73, and CLEC2D, which consistently emerged across multiple models as potential biomarkers for early diabetes prediction." (PMID 40740938, 2025).
psoriasis (1 paper, 2015). An autoimmune condition characterized by red, well-delineated plaques with silvery scales that are usually on the extensor surfaces and scalp. "All other DEGPs could be placed along a continuum, with some showing greater psoriasis specificity (e.g., DBI, GLTP, HRNR, KRT73, ELOVL7), and others showing similar expression shifts in many or most skin diseases (e.g., MX1, S100A8, S100A9, STAT1, LAP3)." (PMID 26251673, 2015).
tumor (4 papers, 2021 to 2026). "Conversely, genes related to epithelial differentiation and keratinization (FLG, FLG2, HRNR, TCHH, KRT73), immune regulation and tumor suppression (HLA-G, UNC5D), and metabolic signaling were downregulated, reflecting loss of tissue integrity and immune control." (PMID 41900972, 2026). "Conversely, KRT73, associated with epithelial differentiation, showed a downregulation trend, potentially reflecting epithelial–mesenchymal transition (EMT) and loss of epithelial polarity during tumor progression." (PMID 41373777, 2025).
KRT73 also shares sentences with these, for which no sentence is quoted: cancer (3 papers); asthma (1); endothelial dysfunction (1); Hypertension (1); latent infections (1); primary effusion lymphoma (1).